IGF1R (insulin like growth factor 1 receptor)
Diseases named in the same sentence as IGF1R in open-access papers (continued):
Sharing a sentence is not in itself a finding about the gene and the disease.
polycythemia (1 paper, 2016). Abnormally high mass or concentration of red blood cells in the blood, either due to an increase in erythropoiesis or a decrease in plasma volume. "Untreated PV patients had significantly higher IGF-1R (361.5, 227.8–461.1) than did secondary polycythemia patients (58.13, 15.46–90.43), normal controls (49.20, 14.63–113.5), and treated PV patients (52.29, 23.89–149.3) (P<0.05)." (PMID 27812134, 2016). "Logistic regression showed that IGF-1R was a statistically significant (P = 0.003) predictor of a patient's group (PV or secondary polycythemia)." (PMID 27812134, 2016). "Significantly elevated IGF-1R values were found in PV patients, while no secondary polycythemia patients had high IGF-1R." (PMID 27812134, 2016). "Hence, we revisited the IGF-1R pathway in PV and found increased IGF-1R expression by flow cytometry in nearly 90% of patients with PV but not in secondary polycythemia." (PMID 27812134, 2016).
Prader-Willi syndrome (1 paper, 2022). "PofOm enrichment at SoC-CpGs is driven by a large PofOm region spanning 6 CpGs on chr15 at IGF1R; along with two singleton PofOm SoC-CpGs, one on chr18 close to PARD6G and the other in the Prader-Willi syndrome-associated imprinted region neighbouring MAGEL2, also on chr15." (PMID 35188105, 2022).
Primary Hypertension (1 paper, 2024). "Chronic, low-grade, systemic inflammation that characterizes primary hypertension may influence changes in the expression level of IGFBP-binding proteins, which may limit the bioavailability of IGF-1, change the IGF-1/IGF-1R signaling, and IGF-1R receptor resistance to IGF-1 binding." (PMID 38540997, 2024).
Primary microcephaly (1 paper, 2020). Head circumference below 2 standard deviations below the mean for age and gender at birth. "Three common mutations of IGF-1R and deletion of the chromosome region containing AKT3 have been identified in patients with primary microcephaly, suggesting that IGF-1R mutations and AKT3 deletion may contribute to this neurodevelopmental disorder." (PMID 32324743, 2020).
primitive neuroectodermal tumor (1 paper, 2025). A malignant neoplasm that originates in the neuroectoderm. "Across all trials, 723 patients with ES/Ewing Family of Tumors (EFT)/Primitive Neuroectodermal Tumor (PNET) were treated with anti-IGF-1R therapy." (PMID 41347090, 2025).
progerias (1 paper, 2018). "Unlike classical progerias, they do not display nuclear/genomic instability, reduced stemness potential of stem cells, or hyperactivation of IGF‐1R signaling." (PMID 30051577, 2018).
promyelocytic leukemia (1 paper, 2011). "Furthermore, IGF-1R was also down regulated in NB4 (promyelocytic leukemia) cells infected with miR-223." (PMID 22073238, 2011).
pterygium (1 paper, 2023). A wedge-shaped fibrovascular lesion arising from the bulbar conjunctiva and extending to the cornea. "Using an immunohistochemical approach, we demonstrated an intense colocalized epithelial overexpression of IGF-2 and IGF-1R in most pterygium samples (Fisher’s exact test, p = 0.021)." (PMID 36901760, 2023). "Therefore, we envision that IGF-2/IGF-1R co-expression in most pterygium samples would favor their interplay through the two different paracrine/autocrine IGF-2 routes for signaling transduction." (PMID 36901760, 2023). "However, the finding of 11 IGF-2+/IGF-1R- samples led us to speculate that the IGF-1R-mediated PI3K/AKT pathway would not be the unique or the main pathway activated in pterygium." (PMID 36901760, 2023).
reflux esophagitis (1 paper, 2016). "(2010) studied IGF Axis Polymorphisms and reported SNPs in three genes (IGF1, IGF1R, and GHR) to be associated with BE, EAC, or reflux esophagitis." (PMID 27468417, 2016).
renal tumors (1 paper, 2013). "Increased levels of Glut1 and IGF1R expression, high Ki67 labeling index, and a dense network of CD34+ microvessels in renal tumors was consistent with increased 18F-FDG accumulation." (PMID 22875335, 2013).
Respiratory insufficiency (1 paper, 2019). "Furthermore, deletion of the gene encoding Igf1r, which mediates the growth-promoting actions of both Igfs, resulted in birth weights that were only 45 percent of normal and these mice generally died within hours after birth from respiratory insufficiency due to muscular hypoplasia." (PMID 30859796, 2019).
retinal disease (1 paper, 2022). "Activation of IGF-1R in retinal disease might prevent the loss of photoreceptors in aging." (PMID 35840554, 2022).
ring chromosome 15 syndrome (1 paper, 2017). "In several cases of ring chromosome 15 syndrome, the IGF1R gene is deleted suggesting a role of IGF1R in the observed growth retardation." (PMID 28899882, 2017).
salivary gland tumors (1 paper, 2015). "We previously demonstrated that genetic ablation of Furin in salivary gland tumors interfered with IGF signaling since it resulted in an impaired processing of the IGF1R." (PMID 26167473, 2015).
serous carcinoma (1 paper, 2024). "In this study, we showed that IGF-1 is overexpressed in high-grade serous carcinoma (HGSC) cell lines, specifically OVCAR3 cells, at both mRNA and protein levels, being a good cell line model to study the IGF-1 inhibition via knockdown of this gene by siRNA or IGF-1R inhibition with linsitinib." (PMID 39596005, 2024).
Short stature (1 paper, 2021). A height below that which is expected according to age and gender norms. "Entire gene deletions and/or mutations causing loss of protein function in SHOX, IGF1R, NPPC, and NPR2 have been reported in familial short stature with various degrees of severity 18,37–40." (PMID 33850126, 2021).
Sjögren’s Syndrome (1 paper, 2021). "This study aims to investigate whether genetic variations of the IGF1R contribute to Sjögren’s syndrome (SS) pathogenesis and explores potential functional implications." (PMID 34501407, 2021).
small intestinal adenoma (1 paper, 2011). "The reduction in small intestinal adenoma volume remains when compared with gefitinib treatment alone reinforcing the potential therapeutic advantage of adding IGF1R blockade to gefitinib." (PMID 21811251, 2011). "We observed that exposure to chronic IGF1R inhibition may delay small intestinal adenoma growth, whereas combined IGF1R/EGFR blockade suppresses growth relative to single agent treatments." (PMID 21811251, 2011).
solitary fibrous tumor (1 paper, 2011). Solitary fibrous tumor (SFT) represents a diverse group of ubiquitous rare spindle cell neoplasms that may be benign or malignant and that most frequently arises from the pleura and peritoneum and rarely from other sites such as head and neck, liver and skeletal muscle. "In addition, IR-A is frequently expressed in solitary fibrous tumors samples (whilst IGF1R is not usually detected) and is essential for virus-induced malignant transformation in Kaposi's sarcoma." (PMID 21437217, 2011).
spinocerebellar ataxia type 1 (1 paper, 2018). Spinocerebellar ataxia type 1 (SCA1) is a subtype of type I autosomal dominant cerebellar ataxia (ADCA type I) characterized by dysarthria, writing difficulties, limb ataxia, and commonly nystagmus and saccadic abnormalities. "For example, it was shown that the IGF1R and RAS–MAPK–MSK1 signaling pathway could be a cause of spinocerebellar ataxia type 1 (SCA1) development." (PMID 30621751, 2018).
tauopathies (1 paper, 2025). "This targeted analysis was instrumental in uncovering the H4R3me2a/miR‐448/IGF1R axis as a key pathway in the context of tauopathies." (PMID 40344412, 2025).
thyroid autoimmunity (1 paper, 2019). "Adding to the continuum of molecules participating in the story of thyroid autoimmunity of GD, the partaken by insulin-like growth factor-1 receptor (IGF-1R), which is stimulated by IgG, need a special mention here." (PMID 30881358, 2019).
toxoplasmosis (1 paper, 2020). A parasitic disease contracted by the ingestion or fetal transmission of toxoplasma gondii. "Still, little is known about the expression of insulin-like growth factor-1 receptor (IGF-1R) during toxoplasmosis." (PMID 32802484, 2020).
tuberculosis (1 paper, 2022). A chronic, recurrent infection caused by the bacterium Mycobacterium tuberculosis. "In search of new chemotherapeutics for tuberculosis (TB), we screened repurposing compounds against the essential glutamine synthase (GlnA1) of Mycobacterium tuberculosis (Mtb) and identified linsitinib, a clinical-stage drug originally targeting kinase IGF1R/IR as a potent GlnA1 inhibitor." (PMID 36048501, 2022).
tumor (1,563 papers, 1992 to 2026). "As for IGF1R rs2016347, the TT genotype was associated with shorter disease-free survival than A allele carriers within the well-differentiated tumour group (p = 0.028)." (PMID 41636865, 2026). "The present study demonstrated an association of IGF1R and IR plasma membrane localisation, as well as IR expression, with a worse tumour behaviour in ACC." (PMID 40038716, 2025). "Genotype (such as PTEN deletion status), tumor tissue IGF-1R expression level, etc., interact with the risk effect of IGF-I, further weakening the dose-response trend in the overall population." (PMID 41584612, 2025). "IGF1R protein expression is associated with tumour progression, while co-overexpression of EGFR and IGF1R has been independently confirmed in 64% (48/75) of ESCC patients." (PMID 40615716, 2025). "Resistance to CSF-1R inhibitors is likely mediated through the interaction of insulin-like growth factor-1 (IGF-1) and tumor cell IGF-1 receptor (IGF-1R), causing an upregulation of the phosphoinositide 3-kinase (PI3K) pathway." (PMID 40427130, 2025). "Mechanistically, crystal structure analysis revealed Tyr333 and Asp335 as key PTPN9 residues interacting with IGF1R; mutation of these residues restored IGF1R signaling and abolished the tumor-suppressive effect of PTPN9." (PMID 41275311, 2025). "Clinically, the increased expression of IGF1R was associated with high tumor grade and poor prognosis in OSCC patients, and its inhibitor linsitinib had synergistic effects with cisplatin treatment in vitro and in vivo." (PMID 39901877, 2025). "Its presence is associated to a less aggressive tumour behaviour, potentially due to its role in negatively regulating IGF1R signalling." (PMID 39528354, 2025). "TNBCvax, which targets three key tumor-associated antigens (TOP2A, HIF-1α, and IGF-1R), offers superior tumor prevention and immunogenicity compared to single-antigen vaccines." (PMID 40969744, 2025). "Higher levels of IGF-1 or IGF-1R are linked to enhanced cell proliferation, skin hyperplasia, and tumor formation." (PMID 39638246, 2024). "Conversely, recent evidence strongly indicates that the IGF-1/IGF-1R signaling pathway plays a significant role in promoting tumor metastasis and drug resistance associated with epithelial-to-mesenchymal transition (EMT)." (PMID 39638246, 2024). "Deficiency of IGF1R in the lung tumor microenvironment (TME) impedes tumor initiation and progression by reducing inflammation and mitigating immunosuppression within lung tumors." (PMID 39328205, 2024). "In renal cell carcinoma, embryonal rhabdomyosarcoma, and synovial sarcoma, nuclear IGF1R in patients is associated with poor prognosis and tumor progression." (PMID 39404930, 2024). "It is known that G12D‐mutated tumor cells can signal oncogenic stimuli to stromal cells, the later promoting IGF1R, AXL and AKT signaling and providing a high level of complexity." (PMID 38650175, 2024). "Insulin-like growth factor 1 receptor (IGF-1R) signaling is implicated in tumor development and progression and induces apoptosis of cancer cells following functional inhibition." (PMID 38665430, 2024). "In patients with PDAC, research has indicated elevated levels of IGF-1R expression within tumors, which has been linked to more advanced tumor grades and poorer survival outcomes." (PMID 39638246, 2024). "The IGF1 - IGF-1R signaling pathway regulates numerous cellular phenotypes associated with tumor cell survival and growth – including cell cycle progression, apoptosis and differentiation." (PMID 37858153, 2023). "We previously found that tumor-associated myeloid cells support T-ALL growth by activating IGF1R signaling." (PMID 37805579, 2023). "Clinically, enhanced IGF1R expression was associated with higher tumour stages and a poorer prognosis in OSCC patients, and its inhibitor, linsitinib, showed synergistic effects with DDP therapy in vivo and in vitro." (PMID 36978187, 2023).
tumor (continued). "Loss of IGF-1R ameliorates the tumor-promoting effects due to enhanced proteasomal degradation of β-integrin subunits." (PMID 36831629, 2023). "IGF2-expressing tumor cells interact with IGF1R-expressing tumor-associated erythroid cells in the patient, and tumor cells expressing SPP1 interact with tumor erythroid cells expressing ITGA4." (PMID 37894821, 2023). "Other cancer-linked phenotypes regulated by IGF-1R signaling include cell adhesion and migration, cancer metastasis, anchorage-independent growth, tumor angiogenesis, and the epithelial to mesenchymal transition." (PMID 37858153, 2023). "Overexpression of IGF1R has been shown in canine OS and is strongly linked to tumor staging and dismal outcome." (PMID 37441462, 2023). "Although tumor-associated myeloid cells promote T-ALL progression by activating IGF1R signaling, which is required for initiation and growth of T-ALL44, exogenous IGF1 alone is not sufficient to support T-ALL survival." (PMID 37805579, 2023). "IGF1R down-regulation inhibits the growth of tumor cells and renders HNSCC cells to be more susceptible to cisplatin in the laboratory." (PMID 36983670, 2023). "Another study conducted by the same group using the mouse pheochromocytoma cell line (MPC) demonstrated that IGF1R deficiency in fibroblasts had effects on the survival of Pheo cells before tumour establishment." (PMID 37033265, 2023). "In a study of 222 British patients with ER+ mBC treated with tamoxifen, a polymorphism of the IGF1R gene was found to significantly increase the risk of tumor progression and death." (PMID 37237509, 2023). "It is associated with tumor prognosis, and crosstalk between IGF-1R and PI3K/Akt and Ras/Raf/ERK signaling pathways is an important factor in the progression and drug resistance of various tumors." (PMID 36698167, 2023). "Insulin-like growth factor receptor 1 (IGF1R) is a transmembrane heterotetrameric protein, encoded by a gene located on chromosome 15q26.3, involved in promoting tumor cell growth." (PMID 37089959, 2023). "Under CSF-1R inhibition, the tumor microenvironment drives treatment resistance via stimulation of the PI3K signaling caused by tumor cell IGF-1 receptor (IGF-1R) and macrophage-derived insulin-like growth factor-1 (IGF-1)." (PMID 37012233, 2023). "LLC primary tumors generated in IGF1R-deficient mice showed delayed tumor implantation and progression." (PMID 35688943, 2022). "The elevated expression and activity of IGF-1R are observed in many cancer types and are associated with tumor cell proliferation, survival, anti-apoptosis, and drug resistance." (PMID 35931997, 2022). "EMT, a key indicator of early stage NSCLC, was reported to promote tumor growth and invasion, and was associated with increased IGF1R expression." (PMID 35688943, 2022). "Expression of IGF1R has been implicated in tumor oncogenesis by promoting tumor cell proliferation and survival." (PMID 36568144, 2022). "Expansion of the metastatic bipotential and basal populations is consistent with increased metastasis in the IGF1R deficient tumor models." (PMID 36568144, 2022). "In this refined gene set (IGF1R-GS2), we identified four gene co-expression modules significantly correlated with low IGF1R (correlation score ≤ -0.25), all of which were also associated with high tumor grade and three of which were associated with TNBC." (PMID 36568144, 2022). "The insulin-like growth factors (IGFs), IGF-1 and IGF-II, which bind to the IGF receptor type 1 (IGF-1R) and the insulin receptor (IR), have been implicated in the growth, survival, and metastasis of tumor cells." (PMID 35399718, 2022). "In this mouse line, the loss of IGF1R function results in decreased tumor latency and increased lung metastases, while tumor growth is unchanged." (PMID 36568144, 2022). "It is clear from the spontaneous tumor models attenuated or loss of IGF1R decreases tumor latency and increases metastasis." (PMID 36568144, 2022).